IRF3 (interferon regulatory factor 3)
Diseases named in the same sentence as IRF3 in open-access papers (continued):
Sharing a sentence is not in itself a finding about the gene and the disease.
cancer (continued). "This, in turn, triggers conformational changes in STING, activating TANK-binding kinase 1 (TBK1), which phosphorylates IFN regulatory transcription factor 3 (IRF3) and promotes type I IFN expression in cancer cells or antigen presenting cells." (PMID 40342534, 2025). "Mechanistically, we demonstrated that OMVs act as natural STING agonists, specifically delivering internal dsDNA into cancer cells and triggering activation of the cGAS/STING/IRF3/IFN‐I axis and ICD occurrence." (PMID 40240911, 2025). "In contrast, human cancer cell lines co-expressing functional cGAS and STING exhibit activation of the cGAS-STING pathway (evidenced by TBK1/IRF3 phosphorylation and ISG expression) upon cytosolic DNA sensing yet fail to secrete IFN-β." (PMID 41007720, 2025). "Mechanistically, AOH1996 induced cellular DNA damage, suppressed cancer stemness through the upregulation of p-TBK1, and promoted the secretion of CD8+ T-cell-recruiting chemokines by stimulating IRF3-mediated transcription." (PMID 41024256, 2025). "All cancer cell lines as well as Nuli-1 showed phosphorylation of STING, TBK1, and IRF3 after stimulation with HT-DNA, indicating an active signaling pathway." (PMID 40012911, 2024). "EV MDA5 agonism has an intriguing innate footprint, characterized by polar TBK1-IFN regulatory factor 3 (IRF3) signaling, which fuels sustained type-I IFN release to provide context for antitumor CD8+ T-cell priming after in situ cancer vaccination." (PMID 37962360, 2023). "Taken together, the available research indicated that FOXP3, IRF3, CD274, and TP63 play an essential role in cancer, even in GBM." (PMID 35401877, 2022). "The TLR3 agonist Poly(I:C) induced the expression of the IRF3 target genes IFNB and CXCL10 in all tested cancer cell lines suggesting that defects upstream of TBK1/IKKe render the cancer cells unresponsive to STING agonists." (PMID 33790360, 2021). "These channels allow the transfer of the second messenger, cGAMP, from cancer cells to adjacent astrocytes to activate STING, thereby triggering TBK1 and IRF3 and producing IFN-α and TNF-α." (PMID 35046953, 2021). "Analyzing protein expression levels in CRC and normal tissues with the HPA database revealed that IRF3 and IRF7 were upregulated in cancer tissues." (PMID 34488791, 2021). "Distinct from the dsRNA-mimetic poly(I:C), the cytotoxicity of siRNAs targeting non-human species-specific lncRNAs exhibits specificity towards human cancer cells and was independent of IRF3, suggesting a novel mechanism." (PMID 39440066, 2024). "The phosphorylated TBK1 and IKK stimulate the transcription factors interferon nuclear factor κB (NF-κB) and interferon regulatory factor 3 (IRF3), eliciting the expression of proinflammatory cytokines such as interleukin 6 (IL-6) and type I interferons (IFN-I) to kill cancer cells." (PMID 38999073, 2024). "No IRF3 reporter activity was seen in STING knock out (KO) THP1 cells in co-cultures with cancer cells, confirming that the IRF3 reporter activity is dependent on STING activation." (PMID 38992037, 2024). "STAT2 binds to STING, modulating its function by inhibiting the expression of IRF3-dependent antitumor genes, but not of NF-κB–dependent protumor genes, thus helping cancer cells to resist DNA damage." (PMID 37036972, 2023). "It has been reported that TFs mediate the functions of lncRNAs in several essential biological processes, such as the lnc-ISIR/IRF3 axis in autoinflammation, the lnc-MAF/MAFB axis in epidermal differentiation, and the lnc-ANRASSF1/PRC2 axis in cancer cell proliferation." (PMID 37107173, 2023).
cancer (continued). "IRF3 is activated by several innate immune receptors, including the cGAS/STING pathway, a novel immunotherapy target with ongoing clinical trials in cancer." (PMID 36092893, 2022). "IRF3 is a key YAP activator, implying that its pharmacological targeting with a small compound inhibitor can elicit broadened antitumor effects against YAP-driven human cancers." (PMID 36589680, 2022). "Increased levels of phosphorylated IRF3 but not IRF7 were detected after poly(I:C) electroporation in mammalian carcinomas." (PMID 35737804, 2022). "Therefore, there is a possibility that PARP inhibitor simultaneously suppresses TGF‐β signaling through production of phosphorylated IRF3 by TBK1, and this can be one of the mechanisms of cancer cell death by PARP inhibitor." (PMID 33342034, 2021). "Our results collectively support a direct role for STING signaling in the frequent IL-6 production in response to genotoxic treatment of cancer cells, most often independent of a marked IRF3 signature." (PMID 35087822, 2021). "No nuclear localization of the activation-defective IRF3-GFP mutant A7 (IRF3A7-GFP) was observed in all tested cancer cells upon treatments." (PMID 33790360, 2021). "The studies on cancer-associated chromosomal instability and STING signaling need to include methods other than measurement of phosphorylation of IRF-3 in order conclude that TBK1 is not involved." (PMID 30223576, 2018). "The upregulated DEGs showed various enforced transcription factors’ networks including IRF3, TAL1, JUN, and FOXA, whereas the downregulated DEGs demonstrated dramatic network suppression of E2F1, a cell cycle progressor, and NR2C2, a cancer-promoting orphan receptor." (PMID 37612293, 2023). "In addition, we show that Top1 poisons can activate both IRF3- and NF-kB-dependent genes, however, they cannot in SCLC cancer cells as the cGAS-STING pathway is markedly impaired likely due to several mechanisms including a drastic reduction of STING and/or cGAS expression." (PMID 35794238, 2022). "Interestingly, STING, TBK1, and IRF3 were not phosphorylated after transfection with 3′3′-cGAMP in these cancer cell lines." (PMID 33490069, 2020). "Thus, if cancer and normal cells would differ with regard to TICAM-1 or IRF-3, then such a virus could potentially target specifically cancer cells rather than normal cells." (PMID 28548066, 2014). "In addition, the action of DUSP10 on cancer, inflammation, and immunity may take place through inactivation of its ‘classical’ targets p38 and JNK, but also through ERK or by directly targeting other proteins like IRF3 in a MAPK-independent manner." (PMID 30939861, 2019). "Surprisingly, after the stimulation of cells with IL-1β or TNFα, after mitophagy induction or in cancer dependent on KRAS signaling, TBK1 is phosphorylated whereas IRF3 is not." (PMID 27538435, 2016). "Furthermore, we found that DNA-damage induced R-loops in the nucleus can activate noncanonical STING via NFκB rather than IRF3, and we highlight KIN as a potential novel target for enhancing cancer immunotherapy in ESCC." (PMID 40813768, 2025). "Nuclear translocation of p‐IRF3 was detected only in E‐MSCs cultured with MB231‐DC but not in E‐MSCs cultured alone, which was also impeded by Gap26, suggesting that the gap junction‐dependent activation of STING and its downstream signaling occurred in MSCs following DC with cancer cells." (PMID 38638003, 2024).
bacterial infection (34 papers, 2012 to 2025). "TBK1 has been shown to phosphorylate and activate IRF3/7 in response to viral and bacterial infections, which in turn drives a type I IFN response." (PMID 39415484, 2025). "Bacterial infection significantly upregulated mRNA expression levels of Isg15, Mx1, Mx2, Irf-3, Irf-7, Tlr-2, Tnf-α, Cxcl-1, and Il-6 genes." (PMID 37929187, 2023). "Recently, we have shown that Type 2 transglutaminase (TG2) negatively regulates IRF3/IFNI axis by controlling IRF3 activation, resulting in a reduction of IFNβ expression, thus regulating cellular response to bacterial infections." (PMID 36572679, 2022). "Taken together, our results reveal that NARL in fish is a critical positive regulator of innate immune responses to viral and bacterial infection by suppressing a feedback to NOD1-NF-κB/IRF3-mediated signaling." (PMID 33581111, 2021). "Specifically, TLR9 constitutively associates with Cav-1 and facilitates MyD88-mediated TRAF3 and IRF3 signal transduction, providing the observed InP effect in fatal doses of bacterial infection." (PMID 31534550, 2019). "The GTPase RAB11A is involved in recruitment of TLR4 to phagosomes and IRF3 signaling, both of which are key events in the innate immune response and host defenses against bacterial infection and are highly relevant for IBD." (PMID 25927528, 2015). "IRF3, 5 and 7 coordinately regulate the Type-1 interferon response, which is an integral part of the innate immune response to viral and bacterial infections." (PMID 24994117, 2014). "Together the data demonstrate that IRF-3 is able to activate pathways of innate immunity against bacterial infection that extend beyond regulation of IFN-β production." (PMID 22911267, 2012). "Together, the data demonstrate the importance of IRF-3 to the basic process of phagocytosis, suggesting an interferon-independent role for the transcription factor during bacterial infection." (PMID 22911267, 2012). "Following bacterial infection, IRF3 is responsible for controlling the expression of IFNs and ISGs." (PMID 36817435, 2023). "In addition, IRF3 functions are harmful in other diseases, including liver injury and bacterial infection." (PMID 36507301, 2022). "Moreover, SHP2 modulated the inflammatory response to secondary bacterial infection via interfering with NF‐κB and IRF3 signalling in macrophages." (PMID 31782850, 2020). "Interferon regulatory factor-3 (IRF-3), one of the most studied members of the interferon regulatory transcription factor family, is widely known to play a pivotal role in the activation of interferon genes in responses to viral and bacterial infections." (PMID 29751576, 2018). "However, the role of IRF3 in bacterial infection is less understood." (PMID 36817435, 2023). "AjCRFB5a functions in the host immune response to bacterial infection by activating antimicrobial peptide LEAP2, and it works as a positive regulator of host antiviral immune responses by activating IRF3 and IRF7-mediated type I IFN signaling pathways." (PMID 37835763, 2023). "IRF3 activates type I IFN and ISGs, which function as defences against viral and bacterial infections." (PMID 36817435, 2023). "With these findings in mind, IRF3 and IRF7 seem to exhibit opposing effects during UTI and balance each other in order to achieve an effective but limited innate immune response to bacterial infection." (PMID 35860746, 2022). "To further establish the functional role of RIG-I in glial cells following bacterial infection, we evaluated signaling downstream of RIG-I by assessing the level of IRF3 phosphorylation and nuclear translocation." (PMID 32357908, 2020). "The requirement for activation of IRF3 and IRF7 in the IFN-β response to bacterial infection has been demonstrated in Listeria, C. pneumonia, and Neisseria meningitidis." (PMID 25798928, 2015).
bacterial infection (continued). "Interferon-inducible protein 204 (IFI204; the murine homolog of IFI16) is an AIM2-like, intracellular DNA sensor, reported to facilitate type I interferon responses to intracellular bacterial infection through cGAS, STING and interferon regulatory factor 3 (IRF3)." (PMID 36829255, 2023). "Bacterial infections, particularly Klebsiella, might stimulate the TLR pathway, downstream interferon regulatory factor 3 (IRF3) molecules, and the NF-κB and PI3K/Akt pathways via molecular mimicry." (PMID 37322475, 2023). "Our findings together showed that AjCRFB5a participates in the host immune response to bacterial infection by inducing antimicrobial peptides mediated by LEAP2 and favorably modulates host antiviral immune responses by activating IRF3 and IRF7-driven type I IFN signaling pathways." (PMID 37835763, 2023). "In light of the interaction between NEURL3 and IRF3 or IRF7, we thus hypothesize that NEURL3 can also affect inflammation through the regulation of interferon signaling during bacterial infection." (PMID 35792897, 2022). "Knocking down BCL10 led to higher transcriptional levels of STING and TBK1, but not of IRF3 upon the bacterial infection." (PMID 33806598, 2021). "TRIM21, an autoantigen associated with SLE, has been identified as an ubiquitin E3 ligase that targets the transcription factor IRF3 in order to turn off and limit type I IFN production following detection of viral and bacterial infection by Toll Like Receptors (TLRs)." (PMID 22479513, 2012). "S. aureus infection influenced phosphorylation of TBK1 and IRF3 rather than protein levels of TBK1 and IRF3, indicating that the bacterial infection initiates IFN-β signaling via controlling the activities of these two proteins by posttranslational modification." (PMID 33806598, 2021). "In contrast to the mRNA levels, the bacterial infection did not influence the protein levels of STING, TBK1, or IRF3 from 1 to 24 hpi." (PMID 33806598, 2021). "In the current study, we showed that ecLPS stimulation and bacterial infection induced the phosphorylation of NF-κB, but not MAPKs (P38, ERK) and IRF3." (PMID 32244806, 2020). "In contrast, IRF-3, a transcription factor commonly involved in inducing IFN-β following bacterial infection, was not necessary for IFN production but instead contributed to host defense." (PMID 22911267, 2012).
metabolic disease (8 papers, 2021 to 2025). A congenital disorder (due to inherited enzyme abnormality) or acquired (due to failure of a metabolically important organ) disorder resulting from an abnormal metabolic process. "Together, these results suggest that deficiency of IRF3 resulted in altered adipogenesis and adipocyte functionality which promote the development of metabolic disorders." (PMID 34091599, 2021). "This study suggests a potential link between the aberrant expression of PPP2R1B caused by PM2.5 and the IRF3-mediated inflammatory responses that may contribute to the development of these metabolic disorders." (PMID 40711007, 2025). "However, since both transcription and proapoptotic functions of IRF3 are implicated in viral and metabolic diseases, we sought to conduct a screen that could isolate small-molecule modifiers of IRF3's proapoptotic function." (PMID 34619149, 2021). "The stimulator of interferon genes (STING)-IRF3 pathway has recently been shown to play an important role in immune and metabolic diseases." (PMID 37328804, 2023). "Given the importance of IRF3 in microbial infection and metabolic disease, it is desirable to identify drugs that can manipulate IRF3 functions to benefit the host." (PMID 34619149, 2021). "The stimulator of interferon genes (STING)‐interferon regulatory factor 3 (IRF3) pathway has recently been shown to play an important role in immune and metabolic diseases." (PMID 35174638, 2022). "As a transcription factor, IRF3 has also been observed to bind to the promoters of other proteins and regulate their expression; it is considered a downstream signalling molecule of the STING-IRF3 pathway in metabolic disease." (PMID 38164186, 2024).
inflammation (7 papers, 2014 to 2024). Aberrant reaction of the microcirculation characterized by movement of fluid and leukocytes from the blood into extravascular tissues. "Collectively, the data reported here lend support to a role for IRF3 in driving the IL-23/Th17 axis and the pathogenesis of CNS autoimmune inflammation." (PMID 25069698, 2014). "In addition to the classic TLRs/MyD88/NF-κB pathway, STING/IRF3/NLRP3 signaling is involved in the LPS-induced cardiac inflammation, apoptosis, and dysfunction." (PMID 35721566, 2022). "Our previous studies found that IKKε mediated LSS-induced endothelial inflammation by activating STAT1 and Akt/IRF3 pathways." (PMID 38315275, 2024). "In a model of acute lung inflammation induced by diesel exhaust particles (DEPs), IRF7 was able to induce RAPTOR expression together with IRF3, promote mTORC1 activation and signal transduction, inhibit autophagy, and thus promoting lung injury induced by DEPs." (PMID 37251373, 2023). "In endothelial inflammation, cytosolic mtDNA activates cGAS, which induces the activation of TANK-binding kinase 1 (TBK1) and the phosphorylation of the transcription factor interferon regulatory factor 3 (IRF3), which are involved in vascular inflammation and destruction." (PMID 33115500, 2020).
neurological disease (7 papers, 2017 to 2025). "Increasing studies have provided evidence of the regulatory role of STING/TBK1/IRF3 signaling in various neurological diseases." (PMID 35936778, 2022). "Recent studies using mice with a defect in the type I interferon signaling axis such as Ifnar or Irf3/5/7 knockout mice develop neurological disease and increased viral replication in the brain, spinal cord and testes following ZIKV infection." (PMID 28667332, 2017). "All weanling Irf3-/-xIrf7-/- DKO mice either died or developed neurological disease at 3 dpi for INKV, and at 5–6 dpi for JCV, indicating that signaling through IRF3 and/or IRF7 was critical for the protection of mice from neuroinvasive disease from JCV and INKV." (PMID 35245345, 2022). "Mice deficient in type I interferon receptors or key signaling molecules (IRF3, IRF7, or MAVS) develop neurologic disease following intraperitoneal infection, suggesting that innate immunity is likely responsible for controlling JCV in the periphery and preventing neuroinvasion." (PMID 41313001, 2025). "However, we found that Ifnar1-/-, Irf3-/-xIrf7-/- DKO, and Mavs-/-xUnc93b1.3D DKO mice inoculated with INKV all developed neurological disease." (PMID 35245345, 2022). "The lack of sufficient IFN signaling in the Ifnar1-/-, Irf3-/-xIrf7-/- and Mavs-/-xUnc93b1.3D mice, which all developed neurological disease, may allow JCV to replicate so abundantly that it can overcome this deficiency and induce BBB breakdown." (PMID 35245345, 2022).
infectious disease (5 papers, 2015 to 2025). A disorder directly resulting from the presence and activity of a microbial, viral, or parasitic agent in humans. "In a recent report, an ethanol extract of Dryopteris crassirhizoma displays strong anti-inflammatory activity by suppressing ERK/AP-1 and TBK1/IRF3 pathways, which contribute to its major ethno-pharmacological role as an anti-inflammatory and anti-infectious disease remedy." (PMID 26136733, 2015). "First, IRF3 is constitutively expressed and serves as a prime initiator of type I IFNs, but IRF7 is activated in the late phase of infectious disease and acts as a master regulator to trigger the transcription of type I IFN genes and IFN-stimulated genes." (PMID 41212050, 2025). "IRF3 can be phosphorylated by TANK-binding kinase-1 (TBK1) to participate in STING-mediated inflammatory and immune responses and facilitate the progression of inflammatory and infectious diseases by regulating the transcription of interferons and inflammatory factors." (PMID 38671352, 2024). "In infectious diseases, the common endpoint is the activation of shared signaling pathways: nuclear factor kappa B (NF-κB)signaling, inflammasome signaling, mitogen-activatedprotein kinase (MAPK) signaling and TANK-binding kinase 1—interferon regulatory factor 3 (TBK1–IRF-3)signaling." (PMID 36675530, 2023).